SLC41A2 (solute carrier family 41 member 2)
Description:
Acts as a plasma-membrane magnesium transporter. Can also mediate the transport of other divalent metal cations in an order of Ba(2+) > Ni(2+) > Co(2+) > Fe(2+) > Mn(2+) (By similarity).
Synonyms: DKFZP434K0427; SLC41A1-L1
Tractability: Antibody: UniProt places it where antibodies can reach, with high confidence; its Gene Ontology location is reachable by antibodies, with high confidence; UniProt predicts a signal peptide or a membrane-spanning region. PROTAC: ubiquitination databases record sites on it; its protein half-life has been measured.
Gene: Protein-coding gene on chromosome 12 (104,801,801 to 104,958,759, reverse strand). Ensembl gene ENSG00000136052.
Subcellular location: Cell membrane
Pathways (Reactome):
Transport of small molecules: Metal ion SLC transporters
Gene Ontology:
Molecular function: protein binding; magnesium ion transmembrane transporter activity; monoatomic cation transmembrane transporter activity; transmembrane transporter activity
Biological process: magnesium ion transport; cobalt ion transport; iron ion transport; manganese ion transport; metal ion transport; nickel cation transport; magnesium ion transmembrane transport; monoatomic cation transport
Cellular component: plasma membrane
Genetic constraint (gnomAD): Loss-of-function variants: 21 observed, 42.04 expected, observed/expected ratio (o/e) 0.5, 90% interval 0.35 to 0.72. The synonymous counts are far from expectation, so gnomAD's model fits this gene poorly and the ratio says little. Missense variants: 410 observed, 576.87 expected, observed/expected ratio (o/e) 0.71, 90% interval 0.65 to 0.77. Synonymous variants: 151 observed, 197.01 expected, observed/expected ratio (o/e) 0.77, 90% interval 0.67 to 0.88.
Homologues: Orthologues: chimpanzee SLC41A2 (99% identical), macaque SLC41A2 (99% identical), rabbit SLC41A2 (95% identical), pig SLC41A2 (95% identical), dog SLC41A2 (94% identical), mouse Slc41a2 (91% identical), guinea pig SLC41A2 (91% identical), rat Slc41a2 (91% identical), tropical clawed frog slc41a2 (79% identical), zebrafish slc41a2b (65% identical), zebrafish slc41a2a (50% identical), Caenorhabditis elegans K07H8.2 (38% identical), and 3 more. Paralogues in human: SLC41A1 (54% identical), SLC41A3 (40% identical).
Diseases named in the same sentence as SLC41A2 in open-access papers:
SLC41A2 is named in the same sentence as 7 diseases in open-access papers, as found by Europe PMC text mining. Sharing a sentence is not in itself a finding about the gene and the disease. The quoted sentences say what the papers report.
diabetes (4 papers, 2017 to 2023). "Slc41a2, a plasma membrane magnesium transporter that was previously suggested to be a genetic variant associated with serum magnesium levels and risk for pre-diabetes, was validated by RT-qPCR." (PMID 37855320, 2023). "We, hereby, replicate the findings from previous studies on the effect of TRPM6, SLC41A2 and CLDN19 on diabetes risk." (PMID 28224192, 2017). "Genetic variation in CLDN19, CNNM2, FXYD2, SLC41A2, and TRPM6 significantly influenced diabetes risk (p < 0.05), and for CNNM2, FXYD2, SLC41A2 and TRPM6 this risk was completely mediated by serum magnesium levels." (PMID 28224192, 2017). "Genetics seems to be a vital risk factor for Type 2 diabetes, and serum magnesium levels may modify the risk of diabetes through several magnesium-regulating genes such as TRPM6, CLDN19, SLC41A2, CNNM2, and FXYD2." (PMID 35565766, 2022). "Furthermore, common genetic variation in magnesium regulating genes TRPM6, CLDN19, SLC41A2, CNNM2 and FXYD2 significantly modify the risk of diabetes through serum magnesium levels." (PMID 28224192, 2017).
magnesium deficiency (1 paper, 2024). A nutritional condition produced by a deficiency of magnesium in the diet, characterized by anorexia, nausea, vomiting, lethargy, and weakness. "Magnesium deficiency linked to dysregulated SLC41A2 can lead to neurological symptoms like seizures and muscle spasms, affecting neural function and overall health." (PMID 39238930, 2024).
tumor (3 papers, 2021 to 2024). "Nevertheless, there was no obvious alteration of SLC41A1 and SLC41A2 expression existing in neoplasm tissues and normal tissues." (PMID 34819993, 2021).
SLC41A2 also shares sentences with these, for which no sentence is quoted: breast carcinoma (1 paper); cancer (1); Obesity (1); Type 2 diabetes (1).